INS (insulin)
Diseases named in the same sentence as INS in open-access papers (continued):
Sharing a sentence is not in itself a finding about the gene and the disease.
diabetes (continued). "Monogenic diabetes affects up to 6.5% of autoantibody-negative Norwegian children with diabetes aged under 15 years, with most cases explained by individuals carrying a single, heterozygous gene variant impairing insulin secretion." (PMID 37798422, 2023). "Also, it has been shown in diabetic patients, quality of life (QOL) was associated with factors, such as hyperglycemia, diabetes duration, insulin therapy, sex, age, complications of diabetes-induced oxidative stress, and other comorbidities." (PMID 37599700, 2023). "Studies have repurposed anti-diabetes agents as novel therapeutics for AD, while how impaired insulin signaling and brain insulin resistance occurs remains unclear, urging further exploration." (PMID 37434738, 2023). "In people with type 1 diabetes mellitus, the delay in intestinal glucose absorption with first- and second-generation α-glucosidase inhibitors after a meal can decrease postprandial glucose excursions and insulin requirements." (PMID 37242267, 2023). "Insulin desensitization is found in the brains of PD animal models independently of diabetes, too." (PMID 37791037, 2023). "This case report demonstrates a case of non-ketotic hyperglycemia hemichorea-hemiballismus syndrome in an individual with a history of poorly controlled type 2 diabetes mellitus and a highly elevated hemoglobin A1C (HbA1C), who subsequently improved with insulin therapy." (PMID 37273351, 2023). "Prior intervention had failed because he had a severe distrust of diabetes devices and had a fear of hypoglycemia, exacerbated by a traumatic car accident, challenges in managing his glucose levels, and difficulty obtaining his insulin and medical support for his diabetes." (PMID 37535407, 2023). "Diabetes mellitus comprises a group of metabolic diseases characterized by hyperglycemia, resulting from either insufficient insulin production (type 1 diabetes) or impaired insulin action (type 2 diabetes)." (PMID 37958661, 2023). "In a 9-year prospective study conducted in Sweden, involving nearly 12,000 participants without HF, it was discovered that insulin IR precedes HF and acts as an independent risk factor, regardless of other risk factors such as diabetes." (PMID 37940979, 2023). "Several research groups have focused on transdermal delivery of insulin for diabetes (type 1 and 2) using pulled microneedles and stainless steel microneedles, and reported that noninvasive microneedle application led to rapid drug delivery onset and excellent pharmacokinetic profiles." (PMID 36678906, 2023). "While insulin use preoperatively is a rough predictor of diabetes severity, other tools such as the DiaRem score may be better at determining diabetes disease severity." (PMID 37816973, 2023). "A regular pulse-rich diet can contribute to better glycaemic control, enhanced insulin sensitivity, and could potentially minimize the reliance on diabetes medications—both in terms of variety and dosage." (PMID 37836506, 2023). "Cell therapy for diabetes aims to restore endogenous insulin secretion, and CSE may have an advanced role in this therapy as a cell delivery method." (PMID 37106373, 2023). "The insulin signaling pathway plays an important role in the development of diabetes mellitus." (PMID 36749274, 2023). "We also observed alterations in epigenetic modifiers such as HDAC4, whose mutation impairs β-cell function and insulin secretion, leading to a non-autoimmune paediatric diabetes." (PMID 36870961, 2023). "There are two primary types of diabetes: Type 1 diabetes, previously known as juvenile diabetes or insulin-dependent diabetes mellitus (IDDM), is characterized by an insulin deficiency and necessitates daily insulin therapy." (PMID 38053195, 2023). "A recent study showed that isorhamnetin decreased the expression of mTOR which might be also another mechanism by which isorhamnetin improves insulin sensitivity which needs to be studied in such a model of diabetes." (PMID 36677559, 2023).
diabetes (continued). "The objective of this study was to translate the Barriers to Insulin Treatment Questionnaire (BIT) into Chinese and test its psychometric properties in middle-aged and elderly type 2 diabetes mellitus (T2D) patients using insulin in the Han people of urban China." (PMID 37654567, 2023). "Conversely, people requiring insulin treatment may typically require more nurturant support owing to feelings of powerlessness in managing diabetes, higher emotional distress, and poorer quality of life than during other stages." (PMID 36607714, 2023). "To gain mechanistic insights into adverse effects of maternal hyperglycemia on the liver of neonates, we performed a multi-omics analysis of liver tissue from piglets developed in genetically diabetic (mutant INS gene induced diabetes of youth; MIDY) or wild-type (WT) pigs." (PMID 37414142, 2023). "Studies have demonstrated that anti-inflammatory therapy in diabetes could improve glycemia and increase insulin secretion." (PMID 38057733, 2023). "Importantly, so far only few studies on air pollution-induced diabetes reported insulin levels and if so, mostly unstimulated insulin at a single timepoint." (PMID 36895000, 2023). "More knowledge of the regulation on β-cell insulin release and the function of these molecules is required to clarify metabolism-secretion coupling and finally explore attractive biomarkers or effective therapeutic targets for diabetes mellitus." (PMID 37764809, 2023). "These include neonatal-onset diabetes mellitus (NDM), diagnosed before the age of 12 months, Mutant Insulin-gene Induced Diabetes of Youth (MIDY), often emerging during childhood, and Maturity Onset Diabetes of the Young (MODY), often emerging during adolescence." (PMID 37048081, 2023). "Adherence to insulin therapy is a critical factor for the control of diabetes." (PMID 37240580, 2023). "Other predictors were sex, age, heart rate, blood pressure, lipid profile, fasting blood glucose, waist circumference, parental history of diabetes, patients’ smoking or drinking habits and the treatment of the patients received such as insulin treatment and lipid-lowering treatment." (PMID 36658644, 2023). "Among the drugs used in diabetes, the most frequently prescribed were biguanides (metformin) in 48.38% of the cases, sulfonylureas in 12.70%, fast-acting insulins and analogs in 6.93%, and long-acting insulin analogs in 16.47%." (PMID 37864147, 2023). "One proposed pathogenic mechanism is that an increase in PTH levels is accompanied by an increase in intracellular calcium, thereby reducing insulin-stimulated tissue glucose uptake, leading to insulin resistance, followed by glucose intolerance and, ultimately, diabetes." (PMID 37959184, 2023). "This could be viewed as similar to use of blood glucose for acute management of insulin dose and hemoglobin A1c for longer term assessment of diabetes control." (PMID 37155649, 2023). "The treatment of an animal with diabetes requires the daily administration of insulin, making it necessary to create a routine and financial support, not only for the acquisition of insulin and consumption items, but also for the monitoring costs, exams, and hospitalization." (PMID 36830471, 2023). "Similar findings were obtained in a Canadian population in an observational retrospective study where they included 626 patients who were switched to insulin degludec with a mean follow-up of six months and which resulted in a reduction of HgbA1c by 0.30 in both types of diabetes." (PMID 36601214, 2023). "Contrarily, individuals clinically diagnosed with Alzheimer’s disease and comorbid diabetes, who have been subjected to insulin and oral medication regimens, have a markedly relieved amyloid pathology compared to those without Alzheimer’s disease or concomitant diabetes." (PMID 38105338, 2023).
diabetes (continued). "A major risk factor for fracture nonunion is diabetes mellitus (DM), a multisystem metabolic and inflammatory condition characterized by hyperglycemia and altered insulin signaling." (PMID 37829606, 2023). "Finally, it must be noted that during the past 30 years, there has been a dramatic change in diabetes managementregarding insulin administration, glucose measurement, and types of insulin." (PMID 37371169, 2023). "In the context of insulin sensitivity, PTEN is a dual protein and lipid phosphatase that negatively regulates the insulin signaling pathway, and polymorphisms of the PTEN gene that lead to higher PTEN expression levels have been noted in diabetes." (PMID 37763285, 2023). "Epidemiological analysis showed a negative correlation of serum iron (frozen) with Fins and HOMAB, indicating that IO might affect insulin secretion and eventually induce diabetes." (PMID 37344885, 2023). "Among those who self-reported a prior diagnosis in Bhutan, 88.6% were currently on medication (last 2 weeks) to treat or control their diabetes, whereas in Bangladesh 81.4% and Nepal 76.7% people were currently taking oral hypoglycaemic agents or insulin to control their diabetes." (PMID 37355725, 2023). "However, the administration of WJMSC-CM (P < 0.01) or insulin (P < 0.001) successfully reversed this diabetes-induced reduction in the hippocampal regions." (PMID 37081849, 2023). "Sudden death related to hypoglycemia may present as "dead in bed syndrome," where individuals with insulin-treated diabetes experience nocturnal severe hypoglycemia and are unable to seek life-saving treatment to correct hypoglycemia." (PMID 37200277, 2023). "The selective inhibition of Arx in alpha cells or ectopic expression of Pax4 leads to the regeneration of insulin-producing beta cells arising from alpha cells which results in the alleviation of diabetes symptoms in mice whose beta cells have been chemically damaged." (PMID 37008919, 2023). "Metformin, as an insulin sensitizer, is a first-line drug for the treatment of diabetes and has recently been shown to have other roles in addition to its role in the treatment of diabetes, among which its role in osteoporosis deserves our attention." (PMID 37904346, 2023). "The model showed that being male, taking insulin now, longer duration of diabetes, higher UACR, and lower serum phosphorus were critical factors in determining the risk of DR in patients with T2DM, which has the same part of risk factors as those reported in previous studies." (PMID 37008912, 2023). "MFN1/2 are also demonstrated to be pivotal for glucose-stimulated insulin secretion by controlling mitochondrial DNA content and may be promising targets to restore glucose control in diabetes." (PMID 37215098, 2023). "Caloric restriction- and weight loss-induced insulin sensitivity was associated with decreased NLRP3 and IL-1β expression in subcutaneous adipose tissue, further suggesting that NLRP3 is associated with diabetes and obesity." (PMID 36834674, 2023). "Diabetes mellitus (DM) is a metabolic disorder of multiple etiology characterized by chronic hyperglycemia with disturbances of carbohydrate, fats and protein metabolism resulting from defects in insulin secretion, insulin action or both." (PMID 37231362, 2023). "Diabetes mellitus is a chronic metabolic disorder of carbohydrates, fats, and protein caused by a relative or absolute lack of insulin." (PMID 37569392, 2023). "In addition to diet management and to monitor the childs activity level, diabetes management also requires the need to regularly perform glucose control and to administer insulin." (PMID 37577126, 2023). "Insulin sensitizers are fundamental to treating Type 2 diabetes mellitus (T2DM)." (PMID 38283440, 2023). "Studies have shown that only around one-fourth of persons with diabetes on insulin could achieve glycaemic targets because they might be erroneously taking an insufficient daily dose and incorrectly titrating insulin." (PMID 38076524, 2023).
diabetes (continued). "As a typical endocrine system disease, diabetes is a glucose metabolism disorder caused by a lack of insulin or insulin resistance." (PMID 37888727, 2023). "All patients were on regular insulin and/or oral hypoglycemic agents to control their diabetes." (PMID 36793092, 2023). "However, it is particularly challenging in patients with diabetes undergoing hemodialysis because the kidney is an organ closely related to blood glucose and insulin metabolism, and glucose and insulin are filtered through the dialysis membrane." (PMID 37089609, 2023). "Type 2 diabetes mellitus accounts for the majority of diabetic patients, mainly due to insulin resistance, which reduces the sensitivity of target cells to insulin and the uptake of glucose capacity, which ultimately leads to elevated glucose levels in the blood." (PMID 37965892, 2023). "Third, the two groups were compared by determining the severity of diabetes only based on whether insulin was used." (PMID 36831436, 2023). "Several clinical factors, such as diabetes duration, insulin dose, HbA1c levels, and C-peptide levels, may affect GV." (PMID 36771224, 2023). "Importantly, it was shown that in rats with STZ-induced diabetes, baicalin therapy effectively increased pancreatic insulin content and limited pancreatic lipid peroxide content (detrimental to cell end products of ROS action)." (PMID 38203600, 2023). "Because type 2 diabetes mellitus (T2DM) patients have impaired insulin action and secretion, increasing hepatic glucose production and decreased glucose-induced release from pancreatic cells, which makes it different from other types of diabetes." (PMID 36874339, 2023). "Finally, some essential information, such as socioeconomic factors, hyperglycaemic or hypoglycaemic crises, and insulin types, are unavailable in the National Diabetes Registry." (PMID 37833402, 2023). "Additionally, muscle fiber cross‐sectional area (CSA) was lower with diabetes and the combination treatment with insulin/MyoAb significantly improved CSA in type II fibers." (PMID 38025035, 2023). "One-third used insulin, and 28.0% had diabetes with complications." (PMID 37708338, 2023). "However, the Portuguese National Health Service strongly facilitates people’s access, covering 90-95% of economic costs of all non-insulin glucose-lowering drugs to people living with diabetes." (PMID 36628395, 2023). "Although there is currently no cure for diabetes mellitus, it may be controlled with medications like insulin and dietary changes." (PMID 38005726, 2023). "Diabetes is a metabolic disorder that affects the production of insulin in pancreatic β cells." (PMID 37108202, 2023). "Therefore, this study investigated the effect of three anti-diabetic drugs, metformin, insulin, and sulfonylureas, on hip fractures in patients with diabetes." (PMID 37161384, 2023). "Considering the effect of FMD cycles in causing diabetes regression, but also the effects on insulin, HbA1c, and HOMA-IR shown in this trial, the much smaller diabetes portion in the FMD group compared to the MD group is likely to have affected the statistical significance of the changes." (PMID 40604264, 2023). "A gene set enrichment analysis showed these “top 50 genes” to be over-represented in 38 gene sets (at false discovery rate q-value < 0.01), 25 of which were defined using terms related to metabolic phenotypes of T2D (e.g., ‘diabetes’, ‘hyperglycemia’, ‘overweight’, ‘waist’, ‘insulin’, ‘c-peptide’)." (PMID 37292813, 2023). "All 6 dogs with diabetes mellitus were receiving insulin therapy." (PMID 37815154, 2023). "Also, more than two decades ago the landmark Diabetes Control and Complications Trial demonstrated similar rates of hypertension amongst participants assigned to intensive vs. conventional insulin therapy." (PMID 36920547, 2023).
diabetes (continued). "In order to further our understanding of the potential relationships between carbohydrate intake, glucose/insulin metabolism, and inflammatory status in diabetic patients, it is recommended that future studies incorporate individuals with diabetes into their research." (PMID 38098008, 2023). "I am already preoccupied with my diabetes and insulin shots." (PMID 38036967, 2023). "Other protein-biomarkers have been associated with diagnosis/prognosis/follow-up of specific ADs; for instance, the protein hormone insulin has been correlated with the diagnosis of various types of diabetes and its low circulating levels have been proposed to signify T1D." (PMID 37571553, 2023). "Third, we only described changes in fasting and postprandial blood glucose levels; therefore, we cannot postulate the development of diabetes, and it is necessary to perform glucose and insulin tolerance tests in future studies using STZ-induced type-1 diabetic mice." (PMID 36769259, 2023). "Other mechanisms involved in the association between LLDs and incident diabetes may include impaired Ca2+ signaling in pancreatic β-cells, the down-regulation of GLUT-4 in adipocytes, and compromised insulin signaling." (PMID 37513689, 2023). "In addition to CGMs, people with diabetes also use insulin pump delivery systems (thus replacing multiple daily injections of insulin)." (PMID 37942482, 2023). "Addressing these limitations could strengthen the study's validity and provide a more comprehensive understanding of the complexities surrounding the adoption of wearable insulin biosensors in diabetes management." (PMID 38239544, 2023). "What is the role of basal insulin in type 2 diabetes mellitus?" (PMID 37132569, 2023). "In diabetes management, the artificial pancreas is a prime example of a digital twin-like system that can greatly improve the ability to monitor and predict blood glucose levels and administer insulin based on non-invasive glucose monitoring methods." (PMID 37888133, 2023). "For example, ineffective production of insulin by pancreatic beta cells can lead to diabetes, and this may occur from birth." (PMID 37568877, 2023). "The father has diabetes and needs supplemental insulin therapy." (PMID 36729569, 2023). "A cross-sectional study was conducted at 14 diabetes clinics throughout Bangladesh from November 2021 to April 2022 among adults with T2DM injecting insulin by pen devices or disposable insulin syringes at least once a day for at least one year by purposive sampling." (PMID 36782190, 2023). "ABCC8, KCNJ11 and INS are the most commonly involved genes in this age group and maybe present on a generic monogenic diabetes panel." (PMID 37033247, 2023). "Diabetes mellitus (DM) is a metabolic disease characterized by abnormal blood glucose levels-hyperglycemia, caused by a lack of insulin secretion, impaired insulin action, or a combination of both." (PMID 37242519, 2023). "Moreover, information such as duration of diabetes, the use of insulin/anti-diabetic agents, BMI, age, HbA1c, and C-peptide levels should be recorded to obtain a better comparison among procedures after taking into account predictive factors." (PMID 37241216, 2023). "pichleri has hepatoprotective, nephroprotective and insulin secretion stimulating effects against STZ-induced diabetes and its complications due to its antidiabetic and antioxidant phytochemicals such as apigenin, luteolin, quinic acid, cosmosiin and epigallocatechin." (PMID 37964249, 2023). "Also, controlled diabetes was significantly higher among patients with regular attendance at the diabetes center (P< 0.001), blood glucose self-monitoring (P< 0.001), adherence to insulin treatment, and controlled dietary intake by the parents (P< 0.001)." (PMID 39296354, 2023). "Adhering to insulin therapy is a challenge for people with diabetes." (PMID 37377235, 2023).